LGALS1 (galectin 1)
Diseases named in the same sentence as LGALS1 in open-access papers (continued):
Sharing a sentence is not in itself a finding about the gene and the disease.
cancer (continued). "Our observation that patients that express galectin-1 above median levels have a significant shorter overall is in agreement with these studies as well as with studies in other types of cancer." (PMID 25259711, 2014). "The expression of galectin-1 and galectin-3 mRNA in normal kidney and corresponding cancer tissue was analyzed using quantitative real time PCR." (PMID 24708743, 2014). "Among carbohydrates, the biocompatibility of galactose molecules and their specific recognition by galectins overexpressed in cancer cells (e.g. galectin-1 and galectin-3) have led to the development of galacto-conjugated PSs." (PMID 24763311, 2014). "It has been shown previously that cancer cells expressing PD-L1 on their surface secrete immunosuppressive cytokines Galectin-1, IL-6, IL-10, and TGF-β, which can inhibit cytotoxic CD8+ T cells." (PMID 22496728, 2012). "Galectins, lectins that are known to interact with mucins and alter cancer cell properties, were found to be down-regulated in MUC4 deficient cells (galectin-1)." (PMID 22393391, 2012). "The level of galectin-1 bound haptoglobin in the cancer sera was on average about twice as high (range 0.6–4 fold) compared to the average for control sera, and confirmed by SDS-PAGE." (PMID 22028908, 2011). "The present results demonstrate that a significant fraction of human serum α-2-macroglobulin, IgM and haptoglobin, bind to galectin-1 and that the total amount of galectin-1-binding glycoproteins can be 2–3 times larger in sera of some cancer patients." (PMID 22028908, 2011). "Galectin-1, a beta-galactosidase binding protein, is strongly expressed in a variety of human cancers and has been shown to play a role in PI3K signaling and Akt activation." (PMID 21687633, 2011). "In conclusion, galectin-1 detects a new type of functional biomarker for cancer: a specific type of glycoform of haptoglobin, and possibly other serum glycoproteins, with a different function after uptake into tissue cells." (PMID 22028908, 2011). "For example, in carcinoma cells, relevant glycoprotein ligands of galectin-1 were identified as lamp-1 and lamp-2, carcinoembryonic antigen, and the fibronectin receptor." (PMID 19898636, 2009). "Galectin-1 is frequently upregulated in tumors and contributes to cancer progression." (PMID 42157933, 2026). "Here, we identify galectin-1 as a critical regulator of cancer stem-like properties." (PMID 42157933, 2026). "Few studies have investigated the role of galectin-1 as a target for miR-22-3p in cancer." (PMID 39996781, 2025). "Few studies have been conducted on miR-22-3p that regulates galectin-1 in cancer." (PMID 39996781, 2025). "Galectin-1 regulates different cancer progression pathways depending on the molecular subtype." (PMID 39996781, 2025). "Single-cell-level transcriptomics analysis of glycosylation-related genes and pathways also revealed that LGALS1 is the most commonly upregulated transcript in cancer cells of the eight investigated tumor types, underscoring the significance of Gal-1 in cancer progression." (PMID 40178639, 2025). "Furthermore, cancer-released exosomes carrying immunoregulatory protein galectin-1 (Gal-1) were shown to exert a potent suppressor function in CD8+ T cells." (PMID 41294803, 2025). "The results showed that compared with LGALS1 knockdown, cancer cell metastases could be clearly seen on the surface of lung tissue of nude mice in the mock group." (PMID 40881692, 2025). "Component 2 (cytokine-linked hematopoietic signaling in cancer pathways) comprised proteins involved in chemotaxis, extracellular matrix regulation, and tissue remodeling, including Eotaxin, RANTES, Decorin, FLT3 ligand, Galectin-1, and Gas1." (PMID 41282065, 2025). "Galectin-1 is related to the EMT pathway in several carcinomas." (PMID 39996781, 2025).
cancer (continued). "While low PA is also associated with the development of T2D, cancer, and regulation of human energy homeostasis, there are no studies on the association between galectin-1 and PA, although a recent study found that galectin-3 is associated with VO2peak in men." (PMID 38578722, 2024). "The pharmacological inhibition of galectin-1 may be beneficial in cancers in which galectin-1 is overexpressed and driving cancer progression." (PMID 39596018, 2024). "Galectin-1 is overexpressed in numerous malignant tumors, including GC." (PMID 37328752, 2023). "In addition, LGALS1 is identified as driver genes in the CML cancer subtype 1 and previous works also find that LGALS1 can be selected as a critical biomarker of CML." (PMID 38096269, 2023). "For this reason, we presumed that Galectin-1 would regulate the cancer stemness of HCC." (PMID 37433225, 2023). "A good example is the expression of galectin-1 and galectin-8 in cancer cells." (PMID 37753083, 2023). "In pancreatic stellate cells and CAFs, knock-down of galectin-1 expression could impair fibroblast activation, cancer cell migration and invasion." (PMID 36873388, 2023). "Moreover, it was shown that the uptake of galectin-1 enriched EXs by human cancer cells leads to the upregulation of its intracellular concentration, which strongly affects cancer cell migration." (PMID 36526668, 2022). "This ability is rescued by the re-introduction of LGALS1 into cancer cells." (PMID 35632759, 2022). "LGALS1 overexpression seems a poor prognostice factor for cancer." (PMID 33854625, 2021). "Overexpression of LGALS1 (Galectin-1) suggests that targeting galectin-1 may inhibit cancer progression by modulating immunosuppressive microenvironment." (PMID 34768716, 2021). "Galectin-1 has been found to be involved in therapeutic resistance in a variety of cancers." (PMID 34201887, 2021). "Galectin-1 (Gal-1), a pivotal immunosuppressive molecule, is expressed by many types of cancer." (PMID 34680031, 2021). "In our study, we observed increased Lysotracker staining, suggestive of lysosomal swelling that is considered a typical condition preceding LMP and galectin-1 complexes, a surrogate marker of lysosomal membrane damage, suggesting a possible role of lysosomes in cancer cell death." (PMID 33194631, 2020). "It is also worth noting that these inhibitors have not been tested in tumors associated with endometriosis, but studies suggest that galectin inhibitors could be effective against these forms of cancer if they overexpress galectin-1 or galectin-3." (PMID 32033052, 2020). "The group with weak galectin-1 expression displayed a 3-year OS of 27.3% and a 3-year cancer-specific survival (CSS) of 27.3%; these values were only 5.9% and 7.6%, respectively, in the group with strong galectin-1 expression (p = 0.009 and 0.020, respectively)." (PMID 29378529, 2018). "If this occurred in our orthotopic xenograft model, then primary human PSCs were carried by the PANC-1 cells to the metastatic site, and the primary human PSC-derived Galectin-1 played a sustained role in promoting metastasis and protecting cancer cells from immune cells." (PMID 29156810, 2017). "Together these findings indicate that Galectin-1 promotes cancer progression by activating NF-κB." (PMID 29156810, 2017). "Galectin-1 is a β-galactoside binding protein secreted by many types of aggressive cancer cells." (PMID 28415760, 2017). "To date, many studies have indicated that intracellular galectin-1 promotes cancer progression." (PMID 28415760, 2017). "Glycodendrimers nucleated the formation of glycodendrimer/galectin-1 aggregates such that galectin-1 no longer effectively cross-linked the cancer cells." (PMID 27649167, 2016). "Mucin 1 is another putative cancer cell-surface receptor of galectin-1." (PMID 27649167, 2016). "In this review, the extracellular roles of galectin-1 in cancer processes are discussed." (PMID 27649167, 2016).
cancer (continued). "This study strongly supports the hypothesis that galectin-1 uses multivalent interactions to aggregate cancer cells." (PMID 27649167, 2016). "Inhibition of galectin-1 in CAF decreases the expression of monocyte chemotactic protein-1 (MCP-1/CCL2), which has been implicated in contributing to an immunosuppressive TME, and as an inducer of cancer progression." (PMID 27050278, 2016). "This review summarizes the current understanding of the molecular mechanism of the increased TF occurrence in cancer, the structural nature, and biological impact of TF interaction with galectins, in particular galectin-1 and -3, on cancer progression and metastasis." (PMID 27066458, 2016). "However the cancer regulating mechanisms of galectin-1 in inducing chemoresistance are still unclear and a clear understanding of the underlying mechanisms are much needed to improve the efficacy of the chemotherapy treatment in HCC." (PMID 26859293, 2016). "Contributions from other soluble factors in TEM cannot be excluded, but our series of studies have observed that galectin-1 secreted by cancer is a primary factor responsible for immune surveillance, by both direct and indirect influence, mediated by cancer-galectin-1-CAF axis on DCs dysfunction." (PMID 27050278, 2016). "Galectin-1 has been observed to arbitrate the adhesion of cancer cells to the ECM." (PMID 27649167, 2016). "Compared with the control LYAR-KD cells, the migration and invasion potential of the HCT116 and HCT8 cancer cells overexpressing galectin-1 was significantly increased indicating that exogenous expression of galectin-1 partially restored mobile potential of LYAR-KD cells." (PMID 26413750, 2015). "Our results could imply that the metastatic spread of malignant tumors involves a higher level of galectin-1 in the circulation." (PMID 26589590, 2015). "In order to test the possibility that galectin-1 may be released from cancer cells and CAF, we looked for the presence of galectin-1 in conditioned culture media from EOC cell lines and CAF cells." (PMID 26589590, 2015). "It not only promotes EMT of cancer cells through activation of SNAIL and HMGA2, but also facilitates the invasion and migration of cancer cells via directly activating transcription of a bunch of invasion or migration-promoting factors, such as LGALS1, OPN and RhoA." (PMID 26123544, 2015). "We overexpressed galectin-1 in CD133− cancer cells and downregulated it in CSCs." (PMID 25605013, 2015). "To investigate whether galectin-1 was a key mediator for LYAR-promoted cancer cell invasion and metastasis, we performed rescue experiments in which galectin-1 was overexpressed in LYAR knockdown cells." (PMID 26413750, 2015). "galectin-1 was stained both in cancer cells with a cytoplasmic pattern and in stromal cells." (PMID 26589590, 2015). "Galectin-1 and Galectin-3 were most intensively studied in context of cancer." (PMID 24592356, 2014). "In addition, Galectin-1 mediated attachment of cancer cells to the extracellular matrix and endothelial cells through binding to CD44 and CD326 on murine breast and colon cancer cells." (PMID 24592356, 2014). "Galectin-1 might also be involved in formation of platelet-cancer cell complexes since it was shown to activate platelets." (PMID 24592356, 2014). "Thus galectin-1 detects a specific subset of this serum protein, which occurs at an increased level in sera from cancer patients and has a different function in tissue cells." (PMID 22028908, 2011). "Total IgM was slightly higher in cancer sera but the percentage bound to galectin-1 lower." (PMID 22028908, 2011). "Second, IgA, the major O-glycosylated protein in serum is not bound by galectin-1, and third the major cancer associated O-glycans, the T antigen (Galβ1-3GalNAcα) and Tn-antigen (GalNAcα) are poor ligands to human galectin-1." (PMID 22028908, 2011).
cancer (continued). "Both the IgM and haptoglobin concentrations were similar in cancer compared to control sera, but the percentage bound to galectin-1 was lower for IgM and higher for haptoglobin: about 50% (range 20–80) in cancer sera and about 30% (range 25–50) in healthy sera." (PMID 22028908, 2011). "The studies here provide a novel approach because firstly, the cancer related glycoforms are detected using an endogenous lectin (galectin-1) that they are likely to interact with in vivo, and secondly because we show that this interaction results in a different function relevant for cancer." (PMID 22028908, 2011). "Serum from a cancer patient was subjected to affinity chromatography on immobilized galectin-1." (PMID 22028908, 2011). "This suggests that the IgM induced under the cancer condition may have decreased binding to galectin-1 with possible connection to its origin and function in the immune system." (PMID 22028908, 2011). "Some of us have recently used an anti-galectin-1 antibody for immunohistochemical staining in the same cancer model, and detected small clusters of presumably preneoplastic cells at the corticomedullary junction already one week after starting DES administration." (PMID 16762066, 2006). "The potential effects of OTX008 on thrombosis and hemostasis have not been investigated; therefore, we only speculate that OTX008 may represent a potential therapeutic approach to target galectin-1-mediated platelet adhesion and platelet–neutrophil interactions in cancer." (PMID 36873388, 2023). "Since galectin-1 and galectin-3 are implicated in the increased angiogenesis that drives tumor proliferation and expansion, monoclonal antibodies against these galectins could help mitigate the VEGF pathway and slow cancer progression." (PMID 32033052, 2020). "Hence, LGALS1 may exhibit dual functions on proliferation in a tissue and cellular context dependent manner in different human malignant tumors or cell lines." (PMID 32047564, 2020). "Moreover, galectin-1 is involved in cell transformation via direct interactions with cell surface oncogenic proteins such as integrins, laminin, and fibronectin, leading to subsequent cancer progression." (PMID 28415760, 2017). "Our lab has previously demonstrated that Galectin-1 is only presented on the surface of BCa cells when SUSD2 is present; therefore, SUSD2 presentation of Galectin-1 on the cancer cell membrane may allow direct regulation of macrophage phenotype upon cell contact." (PMID 28475599, 2017). "The source of increased serum galectin-1 in cancer patients remains unclear." (PMID 26589590, 2015). "However, little is currently known about the regulatory mechanism of galectin-1 in cancer." (PMID 26413750, 2015). "Our study demonstrates the increased galectin-1 expression in EOC and stresses the clinical significance of galectin-1 expression in sera and cancer-associated stroma, a finding that could be important for cancer progression." (PMID 26589590, 2015). "The analysis revealed a distinct overexpression of a single isoform for several genes, namely AGBL5, BOP1, FTSJ3, LGALS1, and NOP58, suggesting a dominant role of these isoforms in the cancer phenotype." (PMID 39001461, 2024). "Our study found that LGALS1 and BCLA2 played a cancer-promoting role in AML and were highly expressed in macrophages." (PMID 38205232, 2024). "N-glycosylated VEGFR2 also interacted with galectin-1 and blocked the interaction between anti-VEGFR antibody and VEGFR2, leading to decreased efficacy of anti-VEGF cancer therapy." (PMID 37612293, 2023). "Galectin-1, a known negative regulator of T cells, is highly expressed in PDAC, where it promotes the progression of cancer by inducing abnormal T cell function and apoptosis." (PMID 36428567, 2022).
cancer (continued). "Using gene expression data from NCI-60 and the Cancer Cell Line Encyclopedia (CCLE), we found that LGALS1 mRNA expression levels anti-correlated with EC50 values, suggesting that cells expressing higher levels of LGALS1 may be more susceptible to virus killing activity." (PMID 35632759, 2022). "After the analysis of fold changes, upregulation in the mRNA level of LGALS1, LGALS3, LGALS4, LGALS8, and LGALS9 was detected in cancer patients compared to normal ovarian tissue." (PMID 36050693, 2022). "VIM, LGALS1, SERPINE1, PKP3 and the CDH1‐CDH2 switch were consistently altered in all the EMT models and have all been related to EMT in different cancer types." (PMID 34942055, 2022). "First, galectin-1 can induce the epithelial–mesenchymal transition (EMT), which is a major process during the progression of cancer in the HCC cells of humans." (PMID 34778306, 2021). "In an extension of this work, benzimidazole-1,2,3-triazole hybrid compounds were synthesized as galectin-1 targeted agents based on compound 179 and were evaluated for their activity against NCI-H460, A549, MDA-MB-231, and MCF-7 cancer cell lines." (PMID 34299488, 2021). "Strong staining of Galectin-1 was found in the focus of liver metastases; however, whether Galectin-1 expressing stromal cells are recruited by the metastastic cancer cells or the metastatic PSCs move together with the cancer cells requires further investigation." (PMID 29156810, 2017). "More work into other cancer types will be essential to best understand the full implications of TDE induced CD8+ Ts cells, as well as identifying the role that proteins such as galectin-1 and the RNA content of TDE play in this process." (PMID 28806909, 2017). "The candidate genes including BGN, MMP1, LGALS1, SERPINB5, and TM4SF4 probably correlated with cancer development and the EMT program mediated by the integrated pathway of TGFβ/Snail with TNFα/NFκB." (PMID 28687755, 2017). "Galectin-1 and GLUT1 are glyco-binding proteins overexpressed in cancer cells that play a key role in the uptake and photo-toxicity of with galactose- and glucose- porphyrin conjugates." (PMID 28545086, 2017). "Galectin-1 then directly mediates migration and invasion by competitively binding receptors involved in cell–ECM interactions, which allows cancer cells to detach from the primary site." (PMID 27649167, 2016). "Our previous studies reported that cancer-derived galectin-1 contributes to DC impairment, and that elevated levels of IDO, an important immunosuppression enzyme, are expressed in tolerogenic DCs in the cancer microenvironment." (PMID 27050278, 2016). "Elevated Galectin-1 has been found in CAF and contributes to CAF activation and CAF-mediated cancer progression." (PMID 27050278, 2016). "In concert with the currently observed elevation of galectin-1 in PDR eyes, these recent reports suggest a potential role of altered N-glycan profiles in the angiogenic activity in PDR as well as cancer." (PMID 26648523, 2015). "Similar to what was observed for galectin-1, there was also a decrease in GLUT1 both after PcGal16 uptake and after PDT treatment in HT-1376 cancer cells." (PMID 24763311, 2014). "Both incubation of cancer cells with PcGal16 (i.e. incubation of cancer cells with PcGal16 in darkness) and PDT with PcGal16 induced a decrease in galectin-1 as observed by Western Blotting and immunofluorescence." (PMID 24763311, 2014). "On the other hand, myosin regulatory light chain 2, galectin-1, lipid-binding AI, annexin V, transthyretin, CARD-inhibitor of NF-κB-activating ligand, and actin prepeptide were downregulated in cancer samples." (PMID 23374291, 2013). "In the present study, we confirmed a higher expression level of the examined genes (for PD-L1, Galectin-1, IL-6, IL-10, IDO, and TGF-β) in the cancer patients." (PMID 22496728, 2012). "On the other hand, the most frequently down regulated AM genes are TGFBR2 (7/13 of cancer models), BAG3, CLU, LGALS1, LTBR, SGK (in 6/13)." (PMID 19402918, 2009).